VWF (von Willebrand factor)
Diseases named in the same sentence as VWF in open-access papers (continued):
Sharing a sentence is not in itself a finding about the gene and the disease.
endothelial dysfunction (continued). "In the mirror of our results, we assume that non-0 blood group carbohydrate antigens present on the molecule might influence OPG levels, either by inhibition of protease cleavage or by an enhanced co-secretion along VWF from a triggered vessel-wall with endothelial dysfunction." (PMID 27387019, 2016). "Finally, the endothelial dysfunction marker vWf was elevated in AF patients." (PMID 25884835, 2015). "In the REVERT trial, short-term rosiglitazone therapy significantly lowered insulin resistance, high sensitivity C-reactive protein (hsCRP), and von Willebrand factor (vWF), suggesting that PPARγ agonists may reduce endothelial dysfunction in patients with CKD." (PMID 25371664, 2014). "Endothelial dysfunction can be assessed in several ways, for example, by physiological techniques as flow mediated dilatation and by the measurement of certain markers as endothelin, microalbuminuria, soluble E selectin, cell adhesion molecules, and von Willebrand factor in the peripheral blood." (PMID 24949439, 2014). "Furthermore, albuminuria is related to elevated serum concentrations of von Willebrand factor and other markers of endothelial dysfunction, a factor that might contribute to the formation of microthromboses." (PMID 24278288, 2013). "Von Willebrand Factor may be useful as a biomarker for endothelial dysfunction and damage." (PMID 23866777, 2013). "Endothelial dysfunction implies an alteration in endothelial integrity and, as such, may be assessed by flow-mediated dilatation or by changes in circulating markers, such as plasma vWF." (PMID 23086579, 2013). "Therefore, evaluation of plasma markers of endothelial dysfunction or damage such as von Willebrand factor and soluble E-selectin might be important." (PMID 20485543, 2010). "By using a thrombin generation test with TM, alongside assessments of VWF antigen and ADAMTS-13 activity, we seek to investigate the extent of coagulation abnormalities and endothelial dysfunction in PCS patients." (PMID 39941459, 2025). "Moreover, we focused primarily on inflammatory and hematologic indices; the addition of emerging markers of endothelial dysfunction (e.g., endothelin-1, von Willebrand factor) or systemic inflammation (e.g., interleukin-6, C-reactive protein) may enhance prognostic stratification." (PMID 41303423, 2025). "We conducted a retrospective study to assess endothelial dysfunction by analyzing six serum biomarkers: t-PA, PAI-1, sICAM-1, sVCAM-1, vWF, and sTM." (PMID 40332159, 2025). "This study investigates hypercoagulability and endothelial dysfunction in PCS through thrombin generation and the von Willebrand factor (VWF)/ADAMTS13 axis." (PMID 39941459, 2025). "To provide more direct evidence of endothelial dysfunction, we included IHC staining for VEGF and vWF in aortic vascular tissues." (PMID 40098620, 2025). "Studies further suggest that NETs contribute to endothelial dysfunction, as evidenced by increased endothelial expression of molecules such as ICAM-1, VCAM-1, E-selectin, TF, and vWF." (PMID 40612950, 2025). "Higher intensity of vWF and lower STXBP5, as demonstrated in the CSPH group in our study, supports the role of endothelial dysfunction as an important factor in PH development." (PMID 38603681, 2024). "Furthermore, if endothelial dysfunction is validated in future large-scale studies, ADAMTS13 level and the ADAMTS13/VWF ratio might be used in clinical practice to monitor the progression of endothelial dysfunction, and these biomarkers might become other therapeutical targets in patients with LVNC." (PMID 37297827, 2023). "Endothelial dysfunction biomarkers correlated positively with compact myocardium mass (R = 0.588 for ADAMTS13, p = 0.01; and R = 0.824 for the ADAMTS13/vWF ratio, p < 0.001)." (PMID 37297827, 2023).
endothelial dysfunction (continued). "Similar to “classical” ARDS there are several molecules that have been identified as endothelial dysfunction biomarkers in c-ARDS, such as ACE2 receptor, von Willebrand factor (vWF), angiopoietin-2 (Ang2) and plasminogen activator inhibitor (PAI)-1." (PMID 36941580, 2023). "Endothelial dysfunction triggered by AS-induced changes in WSS leads to the upregulation of adhesion molecules and the release of von Willebrand factor (vWF), a protein involved in platelet adhesion." (PMID 37834945, 2023). "In vitro studies suggest that NETs can promote endothelial dysfunction, as indicated by increased endothelial expression of ICAM-1, VCAM-1, E-selectin, TF, and vWF." (PMID 37081895, 2023). "Endothelial dysfunction is suggested through elevated levels of thrombomodulin, factor VIII, and Von Willebrand Factor (VWF)." (PMID 38203577, 2023). "Patients with LVNC and HFpEF had endothelial dysfunction, expressed by a lower ADAMTS13 level and ADAMTS13/vWF ratio, and the overexpression of Galectin-3." (PMID 37297827, 2023). "In conclusion, the present study showed that children with Graves’ disease experience endothelial dysfunction, as demonstrated by impairment of FMD and raised vWF." (PMID 37022495, 2023). "We showed endothelial dysfunction in cultured CiGEnCs evidenced by enhanced transcription and translaton of ICAM-1, VCAM-1, vWF, and ET-1 in response to Ang II stimulation to simulate the activated renin-angiotensin system in patients with malignant HTN." (PMID 37188751, 2023). "In the current study, we observed that endothelial dysfunction occurs in children with Graves’ illness as evidenced by FMD impairment and elevated vWF." (PMID 37022495, 2023). "For all patients, we performed CMR, speckle tracking echocardiography (STE), and biomarker assessment for HFpEF (NT-proBNP), for myocardial fibrosis (Galectin-3), and for endothelial dysfunction [ADAMTS13, von Willebrand factor, and their ratio]." (PMID 37297827, 2023). "Another repercussion of the endothelial dysfunction in PE is the increase of endothelial activation biomarkers such as intercellular adhesion molecule-1 (ICAM-1), von Willebrand factor (vWF), and Caspase-3 (CASP-3)." (PMID 36358483, 2022). "Regarding platelet activation and endothelial dysfunction markers, TXA2, p-selectin, VWF:Ac and VWF:Ag were found to be increased." (PMID 35626393, 2022). "Furthermore, a recent randomized controlled trial has shown elevated levels of vWF in induced DM/HC (diabetes mellitus/hypercholesterolemia) swine, which developed atherosclerosis, suggesting that vWF might be a potential marker of endothelial dysfunction in people with metabolic syndrome." (PMID 36499242, 2022). "genetic susceptibility related to ABO blood groups is probably mediated through the von Willebrand factor (VWF) and endothelial dysfunction." (PMID 35634344, 2022). "The protein expressions of endothelial dysfunction markers including ICAM-1 and VCAM-1 were upregulated in shFGA and HG groups, while CD31 and vWF were significantly downregulated." (PMID 35399949, 2022). "In addition, we observed increased levels of plasma vWF in platelet depleted mice (37 vs. 23 ng/ml, p < 0.01), a factor synthesized by and stored in endothelial cells and released into the plasma when the vascular endothelium is damaged, indicating endothelial dysfunction in these pups." (PMID 36016884, 2022). "The reported decreased levels of both the von Willebrand factor, and PAI-1, resulting from the intervention, indicate that endothelial dysfunction, as an early sign of vascular damage, is alleviated by the intervention." (PMID 35381849, 2022). "Nevertheless, we showed that RSV incubation downregulates endothelial dysfunction genes such as ICAM-1, vWF, and CASP-3 in endothelial cells and umbilical arteries of patients with PE." (PMID 36358483, 2022).
endothelial dysfunction (continued). "vWF is stored in Weibel–Palade bodies (WPB) in endothelial cells, where it remains inactive, while in endothelial dysfunction, it is excreted from WPB." (PMID 36078114, 2022). "HUVECs incubated with sera of PE patients showed increased expression of endothelial dysfunction marker mRNAs, such as intercellular adhesion molecule-1 (ICAM-1), von Willebrand factor (vWF), and Caspase-3 (CAS-3)." (PMID 36558404, 2022). "Endothelial dysfunction is the most important factor in the microangiopathic process of HUS, and von Willebrand factor (vWF) has been widely proposed as a biomarker of endothelial damage/dysfunction." (PMID 35811684, 2022). "To further investigate the effect of Xuebijing on endothelial dysfunction in CLP rats, we determined the plasma levels of classical endothelial markers ET-1 and VWF in rats." (PMID 36431172, 2022). "Platelet activation and endothelial dysfunction laboratory markers (serotonin, thromboxane A2 (TXA2), soluble p-selectin, and von Willebrand antigen (VWF:Ag) and activity(VWF:Ac)) were also assessed from the same samples." (PMID 35626393, 2022). "In this review we focused on reported data regarding VWF and FVIII, and other markers of inflammation and endothelial dysfunction, evaluating their potential role in cGvHD." (PMID 33995421, 2021). "ET-1, vWF, and ICAM-1 are all biomarkers of endothelial dysfunction and implicate atherosclerosis progression." (PMID 34484820, 2021). "In this review we focused on reported data regarding VWF and FVIII as well as other markers of inflammation and endothelial dysfunction, evaluating their potential role in cGvHD." (PMID 33995421, 2021). "Von Willebrand factor (VWF) and factor VIII (FVIII) are coagulation factors, as well as acute phase reactants indicating endothelial dysfunction and inflammation in different settings." (PMID 33995421, 2021). "Log-IS and log-PCS also correlated with markers of endothelial dysfunction (log-IS and log-VCAM-1, r = 0.55, p < 0.0001; IS and log-vWF, r = 0.30, p = 0.0005; log-PCS and log-VCAM-1, r = 0.52, p < 0.0001; log-PCS and log-vWF, r = 0.40, p < 0.0001)." (PMID 33423673, 2021). "Treatment of human aortic endothelial cells (HAECs) with hippuric acid induced mitochondrial ROS production, reduced eNOS expression and increased expression of endothelial dysfunction markers ICAM-1 and von Willebrand factor (vWF)." (PMID 33668632, 2021). "Von Willebrand factor (VWF), and a disintegrin and metalloproteinase with thrombospondin motifs 13 (ADAMTS-13), are strong markers of endothelial dysfunction." (PMID 34573989, 2021). "Our data showed that the mRNA expressions of vWF, ET, THBD, ICAM-1, and GMP140 were significantly increased, suggesting endothelial dysfunction." (PMID 34576058, 2021). "Elevation of VWF and potential reduction in ADAMTS13 essentially represent biomarkers of endothelial dysfunction, as most recently typified in COVID-19." (PMID 34564132, 2021). "The effects of GR activation are closely related to endothelial dysfunction, inhibition of NO production, NADPH oxidase activation, increase in von Willebrand factor (vWF), and platelet activation." (PMID 33671798, 2021). "Our present findings regarding the concentrations of vWf and PAI-1 are therefore interesting as inflammation and endothelial dysfunction are closely interrelated." (PMID 32078064, 2020). "High VWF levels indicate endothelial dysfunction and liver sinusoidal endothelial cells (LSEC) likely contribute to the increased VWF levels in these patients." (PMID 32052552, 2020). "Thus, the rise in vWF plasma levels in acute MI might reflect a reaction to ischemic injury and endothelial dysfunction, rather than a causal role in MI development." (PMID 33096906, 2020). "What is more, patients with HFRS had higher markers of endothelial dysfunction (Angiopoetin-2, sVCAM-1, PAI-1, ADAMTS13, d-dimer, sP-Selectin, fibrinogen, vWF, sE-Selectin, sPECAM-1, TF and TM) than CCHF patients." (PMID 31357521, 2019).
endothelial dysfunction (continued). "Therefore, circulating vWF levels may be a useful indicator of endothelial dysfunction." (PMID 29409455, 2018). "Significant correlations were found between plasma dp-ucMGP levels and markers for low-grade inflammation (IL-6) and endothelial dysfunction (VCAM and von Willebrand factor)." (PMID 26495126, 2015). "Thus, pathogenesis-related elevations in plasma vWF may be related to endothelial dysfunction." (PMID 25886574, 2015). "In this study, we used VWF, ADAMST13 and D-Dimer to assess endothelial dysfunction and hypercoagulability in DM1 patients with different and progressive levels of renal dysfunction." (PMID 26168189, 2015). "VWF/ADAMTS13 and ADAMTS13 activity/ADAMTS13 Ag ratio have also been described as markers of endothelial dysfunction and a reduced activity of ADAMTS13 was shown to be associated with renal disease in patients with type 2 diabetes mellitus (DM2)." (PMID 26168189, 2015). "These included endothelial dysfunction (flow mediated dilation – FMD) and its biochemical parameter (von Willebrand factor – vWF), measures of oxidative stress (malondialdehyde levels – MDA), and subclinical atherosclerosis (intima-media thickness – IMT)." (PMID 25369080, 2014). "We observed elevated proinflammatory and endothelial dysfunction indices such as BKB1R, ICAM-1, and VWF expression in endothelium following LPS treatment." (PMID 19171072, 2009). "Also, several plasma markers of endothelial dysfunction, such as soluble ICAM-1, soluble VCAM-1, soluble E-selectin, and von Willebrand factor (vWF), are increased in patients with depression." (PMID 40725164, 2025). "It is plausible to assume that since PE is also associated with a complement dysregulation, enhanced inflammation and endothelial dysfunction, ADAMTS13, and VWF levels may also be dysregulated." (PMID 40362344, 2025). "Finally, VWF and ANGPT2 plasma levels are used as markers for endothelial dysfunction in inflammatory disorders." (PMID 40894883, 2025). "This study assessed endothelial dysfunction and platelet activation biomarkers, including PAI, thrombomodulin, von Willebrand antigen (VWF: Ag), von Willebrand factor ristocetin cofactor (VWF: RCo), and P-selectin, to find a reliable biomarker to predict disease severity in COVID-19 patients." (PMID 40699808, 2025). "In addition to TM, other markers of endothelial health, such as von Willebrand factor activity and ADAMTS-13 activity, are important in assessing endothelial dysfunction." (PMID 39941459, 2025). "Moreover, in endothelial cells and umbilical arteries, resveratrol downregulated endothelial dysfunction genes, such as Caspase-3, ICAM-1, and von Willebrand factor (vWF)." (PMID 39596234, 2024). "Furthermore, studies have shown that individuals with prediabetes have elevated levels of von Willebrand factor (vWF) and plasminogen activator inhibitor-1 (PAI-1), both markers of endothelial dysfunction." (PMID 39175055, 2024). "Our in vivo data of proteomics and immunostaining showed that, compared with WT group, MerTK-/- aggravates atherosclerosis in d-flow areas through upregulation of endothelial dysfunction markers (e.g. IL-1β, NF-κB, TLR4, MAPK signaling, vWF, VCAM-1 and p22phox) and mitochondrial dysfunction." (PMID 38646649, 2024). "Endothelial dysfunction in dogs has been assessed by levels of C-reactive protein (CRP), nitrate and nitrite (NOx), l-arginine (l-Arg), asymmetric dimethylarginine (ADMA), symmetric dimethylarginine (SDMA), and the von Willebrand factor (vWF)." (PMID 39451250, 2024). "Further limitations included the collection of samples in different centers and over a long study period, and that we did not measure other parameters indicative for endothelial dysfunction such as von Willebrand factor, soluble TM, or soluble EPCR." (PMID 39335496, 2024). "However, in DAHND, we also found decreases in VWF and FN1 gene expression, consistent with diminished angiogenic tissue properties and decreased endothelial dysfunction, respectively." (PMID 38565563, 2024).
endothelial dysfunction (continued). "Interestingly, in patients with spontaneous bacterial peritonitis, albumin infusion reduced von Willebrand factor, procoagulant factor VIII and endothelial dysfunction." (PMID 36769582, 2023). "In our study, ELISA results validated that syndecan-1, soluble thrombomodulin, and VWF were positively correlated with NET markers, which indicated that NETs may participate in endothelial dysfunction in TBI." (PMID 36802340, 2023). "Endothelial dysfunction, expressed by the lower ADAMTS13 and ADAMTS13/vWF ratio, may play an important role in the mechanism of HFpEF in patients with LVNC." (PMID 37297827, 2023). "Moreover, platelets produce the transforming growth factor (TGF) beta that upregulated endothelial vWF, thrombomodulin (TM), ICAM-1, and VEGF, promoting endothelial dysfunction in in vitro experiments." (PMID 37628933, 2023). "Furthermore, VWF and FVIII have been long recognized as acute phase reactants with elevated levels indicating endothelial dysfunction and inflammation in a variety of disorders, including coronary artery disease, autoimmune disease, trauma, and infections." (PMID 35996516, 2022). "Recently reduced von Willebrand Factor (vWF) levels, as a marker of endothelial dysfunction, were identified as a possible marker of non-hemodynamic non-selective beta blocker effect." (PMID 36389830, 2022). "VWF, including its production and binding to GPIb, collagen and Glycoprotein IIbIIIa, as well as ADAMTS13, have been well recognized as potential therapeutic targets within management of vascular events and endothelial dysfunction." (PMID 34564132, 2021). "Such strategies may include targeting the upregulated VWF or decreased ADAMTS13 activity in patients with cardiac failure, in order to halt persistent endothelial dysfunction and disease progression." (PMID 34564132, 2021). "More intense staining of vWF was observed in the endothelia of both vessels in DOCA-salt rats and SHR, which could confirm impaired endothelial function, as vWF is a marker of endothelial dysfunction." (PMID 34832902, 2021). "VWF acts as regulator in platelet activation and as a biomarker of endothelial dysfunction and inflammation in COPD Increased VWF levels could therefore potentially reflect the persistence of chronic inflammation in COPD." (PMID 34479474, 2021). "We have recently observed a positive correlation between von Willebrand Factor antigen levels as an indicator of endothelial dysfunction and markers of systemic inflammation, independent of HVPG." (PMID 33000389, 2020). "Considering that Von Willebrand factor (VWF) levels is significantly elevated in COVID-19 patients (529 U/dL compared to 100 U/dL, normal) further supports the hypothesis of SARS-CoV-2 induced endothelial dysfunction or damage." (PMID 32660065, 2020). "Obesity causes early endothelial damage since childhood, when high levels of von Willebrand factor (vWF) and plasminogen activator inhibitor (PAI)-1 antigens, well-known markers of endothelial dysfunction, may be detected." (PMID 32582026, 2020). "Besides, high contents of von-Willebrand factor, factors VIII and XIII can potentially lead to hypercoagulation in the setting of endothelial dysfunction, contributing to the development of thromboembolic events." (PMID 30579327, 2018). "The PTX3 levels and other indicators of endothelial dysfunction (like the soluble form of E-selectin (sE-selectin), VCAM-1 (sVCAM-1), MCP-1 (monocyte chemotactic protein-1), and von Willebrand factor (vWF)) were estimated in plasma and serum of 56 women with SLE." (PMID 28546658, 2017). "Since VWF, ADAMTS13 activity and D-Dimer levels are also elevated in DM2 patients with nephropathy, we believe that endothelial dysfunction and hypercoagulability may play an important role in the progression of renal dysfunction in both DM1 and DM2." (PMID 26168189, 2015).